CSH1 (chorionic somatomammotropin hormone 1)
Description:
Produced only during pregnancy and is involved in stimulating lactation, fetal growth and metabolism. Does not interact with GHR but only activates PRLR through zinc-induced dimerization.
Synonyms: PL; hCS-A; CSA; CSMT; FLJ75407; CS-1; GHB3; hCS-1
Tractability: Antibody: its Gene Ontology location is reachable by antibodies, with high confidence; UniProt places it where antibodies can reach, with medium confidence; UniProt predicts a signal peptide or a membrane-spanning region.
Gene: Protein-coding gene on chromosome 17 (63,894,909 to 63,896,661, reverse strand). Ensembl gene ENSG00000136488.
Subcellular location: Secreted
Pathways (Reactome):
Immune System: Growth hormone receptor signaling; Prolactin receptor signaling
Gene Ontology:
Molecular function: protein binding; growth factor activity; growth hormone receptor binding; hormone activity
Biological process: animal organ development; growth hormone receptor signaling pathway; positive regulation of receptor signaling pathway via JAK-STAT; response to nutrient levels
Cellular component: endoplasmic reticulum; vesicle; endosome lumen; extracellular region; cytoplasm; endomembrane system
Genetic constraint (gnomAD): Loss-of-function variants: 8 observed, 11.9 expected, observed/expected ratio (o/e) 0.67, 90% interval 0.39 to 1.21. The upper end of that interval is the gene's LOEUF score, 1.21, which puts it in group 5 of 6, group 1 being the genes least tolerant of losing a copy. Missense variants: 158 observed, 160.37 expected, observed/expected ratio (o/e) 0.99, 90% interval 0.87 to 1.12. Synonymous variants: 55 observed, 67.73 expected, observed/expected ratio (o/e) 0.81, 90% interval 0.65 to 1.02.
Homologues: Orthologues: macaque CSH2 (79% identical), macaque GHV (79% identical), pig GH1 (62% identical), dog GH1 (62% identical), rabbit GHB1 (62% identical), mouse Gh (60% identical), guinea pig Gh1 (59% identical), rat Gh1 (59% identical), tropical clawed frog gh1 (47% identical), tropical clawed frog gh2 (40% identical), zebrafish gh1 (34% identical). Paralogues in human: CSH2 (99% identical), CSHL1 (92% identical), GH1 (85% identical), GH2 (80% identical), PRL (24% identical).
Diseases named in the same sentence as CSH1 in open-access papers:
CSH1 is named in the same sentence as 15 diseases in open-access papers, as found by Europe PMC text mining. Sharing a sentence is not in itself a finding about the gene and the disease. The quoted sentences say what the papers report.
preeclampsia (4 papers, 2012 to 2023). Preeclampsia is a hypertensive disorder of pregnancy that is characterized by new-onset hypertension with proteinuria presenting after 20 weeks of gestation, and depending on mild or severe forms may initially present with severe headache, visual disturbances, and hyperreflexia. "Predominantly placenta-expressed genes, down-regulated in module M1, are regulators of fetal growth (CSH1, HSD11B2), metabolism (ESRRG), estrogen synthesis (HSD17B1), and immune functions (LGALS14), some of which were reported to be down-regulated in preeclampsia." (PMID 30135684, 2018). "► Reduced GH2-2/CSH1-2 transcripts retaining intron 4 only in preeclampsia without SGA." (PMID 22387044, 2012). "Pseudo-time analysis of the EVT1 and EVT2 subtypes suggested that CSH1 and HSPG2 may regulate EVT differentiation, and both are downregulated in preeclamptic EVT, in line with previous placenta transcriptomics of women with both early-onset and late-onset preeclampsia." (PMID 37854606, 2023).
breast carcinoma (3 papers, 2014 to 2024). "To pursue this possibility, we generated lentiviral constructs containing CSH1 variant 1 (the same variant found in breast cancer cells), and used these to infect four different breast cancer cell lines, followed by harvesting of both RNA and protein." (PMID 24475273, 2014). "CSH expression was determined at the mRNA level in breast cancer cell lines (BCC) and primary carcinomas by real-time and conventional PCR and the products verified as CSH1 by sequencing." (PMID 24475273, 2014). "The overall objective was to establish hPL, the product of the CSH1 and CSH2 genes, as a biomarker for breast cancer." (PMID 24475273, 2014). "Interestingly, immunohistochemical staining revealed that protein levels of CSH1 were undetectable in nearly half of the BLCA samples in our local cohort, similar to previous observations in breast cancer." (PMID 38566204, 2024). "Indeed, this study show that CSH1 can replace FST, which is popular for treating breast cancers." (PMID 27147573, 2016).
gestational diabetes (2 papers, 2012 to 2022). Carbohydrate intolerance first diagnosed during pregnancy. "One study reported reduced serum hPL in gestational diabetes while another reported significantly reduced placental CSH1/2 associated with pre-eclampsia." (PMID 36157466, 2022). "We investigated how the mRNA expression profile of placental GH2, CSH1 and CSH2 genes and their alternative transcripts correlates with maternal pre-eclampsia (PE) and/or gestational diabetes mellitus (GD)." (PMID 22387044, 2012).
colon cancer (1 paper, 2016). "We could confirm the beneficial effect of CSH1 in human colon cancer cell line, HCT116." (PMID 27147573, 2016).
depression (1 paper, 2022). "We reported an association between lower placental CSH1/2 at term and both clinically diagnosed depression and questionnaire reported symptoms of depression in pregnancy." (PMID 36157466, 2022).
Insulin resistance (1 paper, 2025). Increased resistance towards insulin, that is, diminished effectiveness of insulin in reducing blood glucose levels. "CSH-1 has insulin-antagonistic effects and contributes to maternal insulin resistance, ensuring increased glucose availability for the fetus, thereby regulating fetal growth." (PMID 41373661, 2025).
lung carcinoma (1 paper, 2016). "Similarly to PGT, CSH1 could abolish the GH-induced γ-tubulin expression as well as MTOC amplification in human lung cancer cell line, A549." (PMID 27147573, 2016).
mesothelioma (1 paper, 2020). A usually malignant and aggressive neoplasm of the mesothelium which is often associated with exposure to asbestos. "All the proteins of the matrisome-specific interactome of the LOX family expressed in ovarian cancer were also expressed in mesothelioma, except cystatin-like 1 (CSTL1), THSD4 (ADAMTSL-6), and chorionic somatomammotropin hormone 1 (CSH1), which were expressed only in ovarian cancer." (PMID 33383846, 2020).
Silver-Russell syndrome (1 paper, 2023). Silver-Russell syndrome is characterized by growth retardation with antenatal onset, characteristic facies and limb asymmetry. "CSH1 is located in a growth hormone locus on chromosome 17; mutation or deletion of this gene is associated with placental prolactin deficiency and the pathogenesis of Silver-Russell syndrome, but its role in regulating EVT differentiation and the pathogenesis of PE is unclear." (PMID 37854606, 2023).
cancer (5 papers, 2014 to 2025). A tumor composed of atypical neoplastic, often pleomorphic cells that invade other tissues. "In all of tested cancer cell lines, CSH1 obviously blocked the translocation of GR in response to GH." (PMID 27147573, 2016). "Notably, CD96 exhibited significant predictive ability for OS in 9 cancers (all P < 0.05), CSH1 demonstrated significance in 3 cancers (all P < 0.05), and OAS1 emerged as a significant predictor in 10 cancers (all P < 0.05)." (PMID 38566204, 2024). "However, CSH1 seems to possess enough potential for anti-cancer theraphy." (PMID 27147573, 2016). "Since CSH1 can block the MTOC amplification, aneuploidy and γ-tubulin deregulation, we assumed that this chemical would be useful for cancer prevention." (PMID 27147573, 2016). "Similarly with cancer cell lines, GH induced the γ-tubulin expression and CSH1 could block it." (PMID 27147573, 2016). "Since, the anti-cancer effect has not been verified in mouse model, it is not proper time to say that CSH1 can replace FST." (PMID 27147573, 2016). "We could also observe the same effect of CSH1 in human RCC cell line (ACHN) as well as other kinds of human cancer cell lines (A549, HCT116 and MCF-7)." (PMID 27147573, 2016).
tumor (3 papers, 2019 to 2024). "However, in contrast to its limited presence in tumor cells, CSH1 levels were significantly elevated in Bregs, which was found to promote their expansion." (PMID 38566204, 2024).
CSH1 also shares sentences with these, for which no sentence is quoted: colorectal cancer (1 paper); Onset (1); ovarian carcinoma (1); Stillbirth (1).